INS (insulin)
Diseases named in the same sentence as INS in open-access papers (continued):
Sharing a sentence is not in itself a finding about the gene and the disease.
diabetes (continued). "Despite the difficulties in adjusting insulin therapy to physical exertion, children with diabetes should be encouraged to practice sports." (PMID 31165264, 2019). "These extra-glycaemic effects are particularly advantageous given the high incidence of obesity and hypertension among patients with type 2 diabetes, and contrasts with other diabetes drug classes including sulphonylureas and insulin." (PMID 30621212, 2019). "Physical activity is important, especially in preventing diabetes, as it enhances insulin sensitivity and improves glycemic control." (PMID 31731609, 2019). "Type 1 diabetes mellitus is prevalent in younger populations with an inability to produce insulin from the pancreas, the organ responsible for insulin secretion and blood sugar regulation." (PMID 30704425, 2019). "Type 2 diabetes was defined by either a lack of rapid insulin requirement or, where insulin treated within 3 years, retained endogenous insulin secretion (C-peptide >600 pmol/L at ≥5 years diabetes duration)." (PMID 31558459, 2019). "That a single plant-based meal can increase postprandial insulin secretion has direct implication for diabetes treatment." (PMID 30813546, 2019). "Our diabetic animals had a type 1-like diabetes phenotype and were treated with long acting insulin analogue to keep blood glucose around 15 mM." (PMID 30943987, 2019). "The relationship between diabetes and cognitive function is thought to be a process mediated by factors such as arteriosclerosis, microvascular disease, glucotoxicity, and impaired insulin action." (PMID 31014232, 2019). "For example, the insulin topic needs many courses, including type 1 diabetes mellitus, what insulin is and its types, insulin regimens, ways to inject, dosing, storage, adverse effects, allergies, and contradictions." (PMID 31077222, 2019). "LPCs stimulate glucose uptake in adipocytes, potentiate glucose-stimulated insulin secretion, and lower blood glucose levels in rat models of diabetes." (PMID 31915678, 2019). "‘They (diabetic patients) should know how to control their diabetes, but some of them are still in denial that they have diabetes and they stop their insulin." (PMID 30621675, 2019). "All possible nocturnal symptomatic hypoglycaemic episodes will be adjudicated by an independent endpoint committee consisting of diabetes specialists blinded to the individual patient’s insulin regimen." (PMID 31337371, 2019). "T2DM is the most common form of diabetes and results from the body’s ineffective use of insulin: it accounts for the vast majority of people with diabetes around the world." (PMID 30678216, 2019). "Our research constitutes a simple but effective method of intelligent insulin release and blood glucose regulation in diabetes." (PMID 31159842, 2019). "Lipolysis-induced lipid accumulation in the liver attenuates insulin sensitivity and increases hepatic gluconeogenesis, responsible for hyperglycemia during fasting in diabetes." (PMID 31382619, 2019). "Diabetes has two main types, in type 1 diabetes which comprises 5–10% of all diagnosed diabetes cases, the autoimmune destruction of pancreatic β-cells leads to the defective insulin secretion." (PMID 31060468, 2019). "The abnormal levels of serum lipids among patients with diabetes are primarily attributed to the increased mobilization of free fatty acids from fat deposits inhibiting hormone-sensitive lipase requires insulin." (PMID 31443712, 2019). "Nevertheless, hyperglycemia was detected 20 days after the initial onset of DRESS, and subsequent fulminant type 1 diabetes mellitus (F1DM) was diagnosed requiring continuous intravenous insulin infusion." (PMID 31379742, 2019). "The PDM-ProValue study investigated the influence of treatment according to integrated personalised diabetes management (iPDM) in comparison with standard treatment in patients with insulin-treated type 2 diabetes (T2DM)." (PMID 30691463, 2019).
diabetes (continued). "In different model systems of diabetes including of human origin, stress-induced nascent granule degradation (SINGD) contributes to loss of insulin along with mammalian/mechanistic Target of Rapamycin (mTOR)-dependent suppression of macroautophagy." (PMID 31346174, 2019). "We observed statistically significant changes for insulin, sulfonylurea and other diabetes medications." (PMID 31238871, 2019). "There was a preference for using WhatsApp (57.3%) which is an instant messaging service, to contact the diabetes education nurse (32.9%) or consult with the diabetes team most frequently (42.7%) on their insulin dose and glucose regulation." (PMID 30015620, 2019). "GLP-1 itself has a glucose concentration-dependent hypoglycemic effect and it stimulates islet β-cells to secrete insulin, inhibit food intake, and improve symptoms of diabetes." (PMID 30823412, 2019). "Diabetes mellitus was diagnosed in 54 (48%) patients, of whom 16% were diet controlled, 69% on oral antidiabetic drugs and/or non‐insulin injectables, and 15% on insulin treatment." (PMID 30836450, 2019). "Ginsenoside Rb1 ameliorated the HFD-induced increase in FBG, impaired glucose tolerance, and reduced insulin sensitivity to exert its anti-diabetes effects in a HFD-induced mouse model for T2DM (p < 0.01)." (PMID 30823412, 2019). "In management of diabetes, implantable telemonitoring devices for multi-parameters including mainly BG-insulin levels monitoring have recently proven to be an effective approach." (PMID 31666818, 2019). "A positive correlation was found between the PD-1 expression and insulin (r = 0.6241, P = 0.0043) and diabetes duration (r = 0.4592, P = 0.0275) in the correlation analysis." (PMID 31008114, 2019). "The cell-free DNA methylation pattern of the insulin gene promoter has been suggested as a marker of pancreatic islet β-cell destruction, and thereby as an early marker of diabetes." (PMID 30953560, 2019). "Analysis of the diabetes panel to determine if the TPM treatment had an effect on metabolic hormones revealed that HF feeding caused an increase in GIP, leptin, and insulin levels and a decrease in ghrelin; consistent with the literature." (PMID 30616618, 2019). "Diabetes mellitus (DM) is a chronic metabolic disorder characterized by hyperglycemia resulting from defects in insulin secretion, insulin action, or in both." (PMID 31779187, 2019). "Although insulin is a key regulatory hormone of glucose disappearance, current therapeutic agents to treat type 2 diabetes mellitus are focused on compounds possessing incretin effects." (PMID 30719284, 2019). "The available approaches for treating diabetes include dietary control, insulin injection, and oral diabetes medications." (PMID 30999617, 2019). "These confirm the close relationship between Opa1 and mitochondrial insulin-stimulated energy metabolism, which provides a basis for its regulatory role in obesity and diabetes." (PMID 31551926, 2019). "Probiotics can affect metabolic syndrome, type 2 diabetes mellitus, and obesity by regulating intestinal microbiota, favoring insulin signaling, and decreasing cholesterol levels." (PMID 31284705, 2019). "Short-term administration of FGF21 reduces insulin levels in both healthy and db/db mice (diabetes mice)." (PMID 30927227, 2019). "Adipose tissue is an important organ involved in the regulation of insulin sensitivity and development of diabetes through its fat storage capacity and thermogenic regulation." (PMID 31541119, 2019). "As PPARγ full agonists, thiazolidinediones (TZDs), such as rosiglitazone and pioglitazone, have been widely used in treating type 2 diabetes mellitus due to their potent insulin-sensitizing effects." (PMID 31581474, 2019). "The All New Diabetes in Scania (ANDIS) study is a large study of more than 14,000 individuals, recruited at or close to diagnosis of diabetes, with insulin, fasting glucose and antibodies measured at recruitment." (PMID 31161345, 2019).
diabetes (continued). "NOD mice also have the advantage of less severe ketoacidosis and thus relatively long survival after diabetes onset, allowing easier set-up of experiments involving insulin treatment and reversal of diabetes." (PMID 31139178, 2019). "Collectively, these findings suggest that pancreatic FGF21 is important for promoting insulin expression and secretion, which in turn protect against the progression of diabetes." (PMID 30461198, 2019). "Administration of exogenous animal insulin for the treatment of diabetes often induces the production of insulin antibodies (IA)." (PMID 31687408, 2019). "Emerging evidence suggests that immune and inflammatory response is a critical driver in the pathogenesis of T2D, including obesity-related insulin resistance, impaired insulin secretion, and diabetes-related vascular complications." (PMID 31681285, 2019). "Nearly all participants had diabetes (99%), for which most were taking medications (i.e., oral antihyperglycemic agents and insulin)." (PMID 31540227, 2019). "Pregnant women with diabetes mellitus had higher rates of central obesity, glucose levels, insulin, triglycerides, total cholesterol, and LDL compared to the control group." (PMID 31807722, 2019). "Three patients (11.5%) developed diabetes mellitus and 2 of them required insulin and 1 required metformin." (PMID 30991953, 2019). "In the group meeting study criteria for type 2 diabetes and treated with insulin at diagnosis, 25% reported a diagnosis of type 1 diabetes, and only 59% received concurrent oral glucose-lowering therapy at a median diabetes duration of 10 years." (PMID 30969375, 2019). "Type 1 diabetes mellitus is a metabolic disease resulting from the destruction of insulin-producing β cells in the pancreas, that leads to hyperglycemia." (PMID 31817632, 2019). "Here the authors show that the FDA-approved drug neratinib has beneficial effects on β-cell survival, insulin secretion, and glycemic control in mouse models of diabetes." (PMID 31676778, 2019). "As a consequence of the increasing incidence of diabetes, the need for insulin and insulin analogs will augment exponentially." (PMID 31798448, 2019). "High levels of insulin autoantibodies, as well as hyperinsulinemic hypoglycemia, are found in patients with diabetes mellitus and prior exogenous insulin exposure." (PMID 31883520, 2019). "Diabetes mellitus (DM) is considered as a group of disorders of heterogeneous etiology, characterized by chronic hyperglycemia and other metabolic abnormalities caused by defects in insulin secretion, insulin action, or both." (PMID 31355291, 2019). "Type 2 diabetes mellitus is a metabolic disorder characterized by hyperglycemia, which arises from insufficient pancreatic insulin secretion, insulin resistance in peripheral tissues, and inadequate suppression of glucagon production." (PMID 30959814, 2019). "Diabetes mellitus is defined as a group of metabolic diseases characterized by hyperglycemia resulting from defects in insulin secretion, insulin action or both." (PMID 31312330, 2019). "In this context, it is relevant that in wild type mice, the C57 genetic background renders the mice more prone to become obese, insulin resistant, and glucose intolerant and develop diabetes." (PMID 31920474, 2019). "On the other hand, sulfonylureas, which remained the second most commonly used diabetes medication class after insulin initiation, had the lowest rate of continuation at 73.6%." (PMID 30759121, 2019). "Post-exercise plasma ARA levels were significantly reduced with carbohydrate intake, and these data imply that PLA2 activity was attenuated, perhaps in part due to higher glucose and insulin levels as extrapolated from diabetes-based investigations." (PMID 30883596, 2019). "Diabetes is a harmful metabolic disease characterized by way of hyperglycemia as results from defects in insulin secretion, insulin action, or both." (PMID 31663031, 2019).
diabetes (continued). "In early 1990s, the Ministry of Health of Brazil launched a National Diabetes Plan, which proposed an equation to calculate the amount of insulin needed per year in Brazil for universal coverage and amplified public purchase of the drug." (PMID 30867683, 2019). "Meeting glycemic targets is a challenging task in young patients with T1D; thus, new insulin delivery systems represent an opportunity to improve glycemic control, to promote patient-centered decisions, and to reduce the burden of diabetes care." (PMID 31685014, 2019). "Recent studies suggest that TUDCA is effective in e.g., increasing insulin sensitivity, potentiating insulin clearance, and increasing pancreatic beta-cell mass in obese humans and murine models of obesity and diabetes." (PMID 31757001, 2019). "Approximately 50% of T2D patients will need insulin therapy within ten years of diagnosis Although in the past diabetes has been called chronic and irreversible, the paradigm is changing." (PMID 30939855, 2019). "Type one DM (T1DM or insulin-dependent diabetes mellitus) is a chronic and progressive disease that results from damaged pancreatic β-cells that secrete insulin." (PMID 30987324, 2019). "And it can help in controlling the weight of the patients on insulin therapy thus preventing the initiation of a vicious cycle of weight gain and then uncontrolled diabetes." (PMID 31576267, 2019). "An animal study has shown that astaxanthin (1.0 mg/mouse/day for 13 weeks) decreases blood glucose levels, improves insulin serum levels, and reduces glucose tolerance in type 2 diabetes mellitus rodent models." (PMID 31075966, 2019). "It has been observed that insulin replacement acutely increases pulsatile LH secretion in rodent diabetes models." (PMID 31620084, 2019). "Diabetes mellitus is a chronic metabolic disease characterized by hyperglycemia due to the defects in insulin secretion, action, or both and it is increasing at an epidemic proportion throughout the world." (PMID 31396287, 2019). "Not only insulin has already been successfully loaded into nanoparticles but also other sugar lowering drugs for the treatment of diabetes and its complications." (PMID 31756981, 2019). "Our finding that Ppp1r15a mutant mice depleted of most beta-cells with streptozotocin have improved glucose tolerance suggests that the beneficial effects on insulin sensitivity dominate in the setting of diabetes." (PMID 30814564, 2019). "Diabetes mellitus is a metabolic disorder characterized by hyperglycemia due to defects of insulin secretion or action." (PMID 31053131, 2019). "For people with diabetes on insulin therapy, education on how to use carbohydrate counting and in some cases fat and protein gram estimation to determine mealtime insulin dosing can improve glycemic control and prevent excessive weight gain." (PMID 31576267, 2019). "There was also a theme identified that MITI addressed just 1 component of diabetes care (insulin titration) and there was an unmet need for additional diabetes support more broadly in the population." (PMID 31368439, 2019). "This table summarises non-insulin diabetes medications (generic and brand names) available in Australia at the time this study was conducted." (PMID 30777033, 2019). "Pathophysiological conditions arise with insulin dysregulation; declines in either insulin’s release or its actual production by β-cells characterizes the main features of diabetes mellitus (DM) development." (PMID 31817135, 2019). "The ORs were adjusted for maternal age and prepregnancy BMI in the first pregnancy, educational attainment, family history of diabetes, and insulin treatment." (PMID 30767767, 2019). "Lower quartiles of serum Mg were associated with increased IMT-CC, and also with age, SBP, fasting glucose, glycated hemoglobin (HbA1c), HOMA-IR, serum corrected calcium, diabetes, oral antidiabetic drugs and insulin use." (PMID 31142774, 2019).
diabetes (continued). "Additional studies with regular LCS consumers, people who are more insulin resistant, and people with diabetes are needed." (PMID 31877631, 2019). "Treatment of non-insulin-dependent diabetes mellitus (NIDDM) due to insulin dysfunction involves inhibiting or delaying intestinal carbohydrate digestion." (PMID 31717970, 2019). "Type 2 diabetes mellitus (T2DM) is a form of diabetes that is characterized by the body's inability to produce insulin." (PMID 31815135, 2019). "Given these important therapeutic considerations, it is necessary to better understand practice patterns in diabetes treatment during the insulin transition." (PMID 30759121, 2019). "An experimental study proposed that isorhamnetin glycoside has several effects on diabetes, like stimulating insulin secretion, the expression of enzymes involved in lipid metabolism, and the expression of endoplasmic reticulum stress markers." (PMID 31480505, 2019). "This study directly compared the risks of cardiovascular disease (CVD) and all-cause mortality among type 2 diabetes mellitus (T2DM) patients receiving DPP4i, TZD, or insulin as a third-line medication." (PMID 31877127, 2019). "This recently FDA-cleared system consists of the insulin pump (“Pod”), which is worn on body and delivers insulin, and the Personal Diabetes Manager (PDM), which is a handheld device used to wirelessly control and monitor the Pod functionality." (PMID 30239214, 2019). "Diabetes was induced chemically with alloxan or streptozotocin, both of which damage β cells and inhibit production of insulin by the pancreas." (PMID 31234300, 2019). "Allergic reaction to insulin is rare, especially when using recombinant human insulin, with a frequency of less than 1% in patients with diabetes." (PMID 31711488, 2019). "Only 3% of CHCs carried at least one type of diabetes medications (metformin, glibenclamide or insulin)." (PMID 30980631, 2019). "PTP1B has gained much attention in recent years due to its ability to attenuate insulin signaling and it is currently regarded as a potential therapeutic target against metabolic syndrome, obesity and diabetes." (PMID 31319588, 2019). "Prescribing of non-insulin diabetes medications at doses inconsistent with current ADS guideline recommendations for dosing adjustments for people with renal impairment was common." (PMID 30777033, 2019). "As the most common form of diabetes, type 2 diabetes is a chronic metabolic disease which is characterized by high blood glucose, low insulin sensitivity." (PMID 31093312, 2019). "FIB is related to insulin sensitivity and insulin resistance causes oxidative stress via thrombin formation and the following FIB synthesis, which promotes diabetes complications and adverse clinical consequences." (PMID 31014348, 2019). "Diabetes mellitus (DM) is a metabolic disease characterized by chronic hyperglycemia and defective insulin secretion, insulin action or both." (PMID 30962863, 2019). "Serum adiponectin enhances insulin sensitivity, and individuals with obesity, type 2 diabetes mellitus (DM), and other metabolic disorders have low serum adiponectin levels." (PMID 31323782, 2019). "In a recent study, researchers have been able to distinguish five distinct clusters of diabetes by combining parameters such as insulin resistance, insulin secretion, and blood sugar level measurements with age of onset of illness." (PMID 31827713, 2019). "Type 2 diabetes, the most common type of diabetes, is characterized by insulin resistance, inappropriate insulin secretion, and hyperglycemia." (PMID 31370156, 2019). "Diabetes is defined as a chronic, multifactorial disorder characterized by the failure of the body to produce insulin (type 1 diabetes) or by defects in insulin action (type 2 diabetes)." (PMID 31121837, 2019).